CR1 (complement C3b/C4b receptor 1 (Knops blood group))
Diseases named in the same sentence as CR1 in open-access papers (continued):
Sharing a sentence is not in itself a finding about the gene and the disease.
melanoma (5 papers, 2011 to 2025). A malignant, usually aggressive tumor composed of atypical, neoplastic melanocytes. "After vaccination, CD8+ T cells isolated from the spleen of a CR-1-vaccinated mouse secreted significant amounts of IFNγ in response to stimulation with B16F10 melanoma cells that express high levels of CR-1 protein." (PMID 34360603, 2021). "They perform in vitro functional analysis of 1B4 mAb by using C8161 melanoma cell line and demonstrated that 1B4 is able to block and interfere with CR-1 signal cascade." (PMID 34360603, 2021). "Our paper is also the first to formally demonstrate that CR-1 can function as an autocrine and/or paracrine growth factor in melanoma cells, in which CR-1 is able to activate both Nodal and Src signalling." (PMID 21863025, 2011). "In conclusion, this study demonstrates that a significant fraction of melanoma expresses CR-1, and that this growth factor is involved in the invasion and proliferation of melanoma cells." (PMID 21863025, 2011). "As expected, Nodal was able to induce Smad-2 activation in the three melanoma cell lines, and its activity was slightly increased by co-treatment with CR-1." (PMID 21863025, 2011). "Expression of CR-1 protein and/or mRNA was found in 16 out of 37 primary human cutaneous melanomas and in 12 out of 21 melanoma cell lines." (PMID 21863025, 2011). "In order to address this phenomenon, we analysed the effects of silencing endogenous CR-1 by transfection of melanoma cell lines with a pool of four CR-1 siRNAs." (PMID 21863025, 2011). "Expression of CR-1 protein in melanomas and melanoma cell lines was assessed by immunohistochemistry, western blotting and/or flow cytometry." (PMID 21863025, 2011). "For this purpose, we assessed the expression of CR-1 in human melanoma biopsy samples and melanoma cell lines, and determined the effects of CR-1 signalling on the growth and invasiveness of human melanoma cells." (PMID 21863025, 2011). "Expression of Nodal, an embryonic growth factor for which CR-1 acts as a co-receptor, is positively correlated with melanoma invasiveness and aggressiveness." (PMID 21863025, 2011). "Although preliminary findings from our group have shown that a subset of melanoma cells also express CR-1 on the cell membrane, the precise role of CR-1 in cutaneous melanoma remains to be determined." (PMID 21863025, 2011). "Anti-CR-1 siRNAs produced a significant inhibition of the growth and the invasive ability of melanoma cells." (PMID 21863025, 2011). "We found that 16 out of 37 (43%) melanoma samples expressed high levels of CR-1 protein." (PMID 21863025, 2011). "Finally, a close correlation was found in melanoma cells between the levels of expression of CR-1 and the effects of saracatinib on cell growth." (PMID 21863025, 2011). "Further studies are in progress to assess whether CR-1-mediated signalling might represent a novel target for therapeutic intervention in melanoma." (PMID 21863025, 2011). "Endogenous CR-1 seems to regulate mainly c-Src activation in melanoma cells." (PMID 21863025, 2011). "In this regard, our findings suggest that expression of CR-1 might significantly enhance the metastatic potential of melanoma cells through the activation of the Nodal/ALK/Smad pathway." (PMID 21863025, 2011). "Our data also suggest that the expression of CR-1 in melanoma cells might represent a marker of Src activation and, therefore, of sensitivity to c-Src inhibitors such as saracatinib." (PMID 21863025, 2011). "In addition, we found that recombinant CR-1 was able to induce a significant increase in the levels of activation of c-Src in melanoma cells." (PMID 21863025, 2011). "Next, we determined whether treatment of melanoma cells with recombinant CR-1 induces the activation of c-Src and Nodal/ALK4/Smad-2 pathways." (PMID 21863025, 2011). "Expression of CR-1 was found in both early and late stages of melanoma development." (PMID 21863025, 2011).
melanoma (continued). "In addition, a time-dependent inhibition of the invasive ability of melanoma cells was observed after silencing of endogenous CR-1 mRNA." (PMID 21863025, 2011). "We next investigated whether the silencing of endogenous CR-1 affects the proliferation and invasive ability of melanoma cells that express high levels of CR-1." (PMID 21863025, 2011). "Recombinant CR-1 protein activated in melanoma cells c-Src and, at lesser extent, Smad signalling." (PMID 21863025, 2011). "Interestingly, a strong correlation was found between the expression of CR-1 mRNA and the response to saracatinib in our panel of melanoma cell lines." (PMID 21863025, 2011). "The observation that CR-1 siRNAs reduced the invasive ability of melanoma cells and the activation of c-Src supports the hypothesis that endogenous CR-1 might induce the growth and invasion of melanoma cells through activation of c-Src." (PMID 21863025, 2011). "First, we analyzed the impact of CR-1-31-B on DUSP6 levels and the ERK pathway activity in A375 melanoma cells using Western blot." (PMID 39436655, 2024). "In order to assess the expression of factors involved in CR-1-mediated signalling, we examined the expression of Nodal, ALK4 and Activin B mRNAs in melanoma cell lines by RT–PCR." (PMID 21863025, 2011). "Expression of CR-1 protein was assessed by flow cytometric analysis in the human melanoma cell lines ROS 184, CON 242 and COPA 159, which show intermediate to high levels of CR-1 mRNA." (PMID 21863025, 2011). "In this regard, we found that the majority of melanoma cell lines that express CR-1 have also transcripts for Nodal and ALK4, suggesting that a Nodal/CR-1/ALK4 pathway might be active in melanoma." (PMID 21863025, 2011). "In agreement with this hypothesis, we found that an exogenous recombinant human CR-1 protein (200 ng ml−1) induced a significant increase in the invasive ability of CON 242, COPA 159 and ROS 184 melanoma cell lines." (PMID 21863025, 2011). "Therefore, we analysed the effects of CR-1 and/or Nodal on the activation of the Nodal/ALK4/Smad-2 pathway in melanoma cells." (PMID 21863025, 2011). "Interestingly, in uveal melanoma the expression of CR-1 was significantly higher in cases with extra-scleral extension/liver metastasis as compared with melanomas with no extension." (PMID 21863025, 2011).
nasopharyngeal carcinoma (5 papers, 2019 to 2023). A carcinoma arising from the nasopharyngeal epithelium. "For example, the expression of CR1 mRNA was upregulated in nasopharyngeal carcinoma, and the risk of death in patients with high CR1 expression was significantly higher than that in patients with low CR1 expression." (PMID 37342563, 2023). "In nasopharyngeal carcinoma (NPC), miR-138-1-3p has been inversely correlated with the expression of CR-1." (PMID 34360603, 2021).
non-small cell lung carcinoma (5 papers, 2014 to 2025). A group of at least three distinct histological types of lung cancer, including non-small cell squamous cell carcinoma, adenocarcinoma, and large cell carcinoma. "In non-small cell lung cancer, CR-1 expression was correlated significantly with poor tumor differentiation, TNM stage, and lymph node metastasis." (PMID 31455359, 2019). "Our results suggest that CR-1 can serve as such a marker for ESCC, which is consistent with the previous reports in cervical carcinoma, gastric cancer, and non-small cell lung cancer." (PMID 28431580, 2017). "In the context of pulmonary malignancies, particularly non-small cell lung cancer (NSCLC), circulating concentrations of Cripto-1 (CR-1) and vascular endothelial growth factor (VEGF) have been shown to be markedly elevated relative to those observed in healthy control cohorts." (PMID 40943351, 2025).
prostate carcinoma (5 papers, 2012 to 2025). A carcinoma that arises from epithelial cells of the prostate gland. "CR-1 is thought to play a vital role in the migration and invasion of several different types of cancers, such as esophagus squamous cell carcinoma and prostate carcinoma." (PMID 30373174, 2018). "In all, these data suggest CR-1 as a new biomarker with potential prognostic value for primary prostate cancer." (PMID 25596738, 2015). "We demonstrate that a region within E1ACR1 (amino acids 48–60) is essential for drug-sensitization, while both E1ACR2 and a region proximal to CR1 (amino acids 26–35) are redundant in our prostate cancer models." (PMID 23056370, 2012).
schizophrenia (5 papers, 2011 to 2025). A major psychotic disorder characterized by abnormalities in the perception or expression of reality. "Here CR1 represents a special interest, accounting for a positive genome-wide linkage of schizophrenia with the CR1 gene encoding locus (1q32)." (PMID 21867543, 2011). "Our results indicated that schizophrenia is associated with the increased CR1 expression and C1q-CIC level." (PMID 21867543, 2011). "In the present study we investigated the expression of CR1 on E and leukocytes in patients with schizophrenia and evaluated the possible association of CR1 C5507G functional polymorphism with this disorder." (PMID 21867543, 2011). "Our study for the first time indicated that schizophrenia is associated with the increased CR1 expression and C1q-CIC level." (PMID 21867543, 2011). "Interestingly, the levels of CR1 expression on E were higher in CR1 5507 CC homozygotes when compared to those in G allele carriers both among the patients with schizophrenia and control subjects." (PMID 21867543, 2011). "In conclusion, on the basis of our results we suggested that schizophrenia is associated with the increased expression of CR1 on E, L, M, and N accompanied by the elevated number of CR1 positive E, reduced number of CR1 positive L and M, and increased level of C1q-CIC." (PMID 21867543, 2011). "According to the data obtained, CR1 expression levels for erythrocytes were significantly higher in patients compared to controls and were positively correlated with the duration of schizophrenia (rho = 0.637, p = 0.004)." (PMID 21867543, 2011). "In addition, in the blood of schizophrenia affected subjects the levels of circulating immune complexes (CIC) containing natural ligands of CR1, namely C1q and fragments of C3, were also determined." (PMID 21867543, 2011). "The present finding of the increased CR1 expression levels on blood cells of schizophrenia patients may be a consequence of the elevated levels of the total population of IC in circulation reported by us previously, as well as increased levels of C1q-CIC reported in the present work." (PMID 21867543, 2011). "In particular, we found negative factors related to AD (including short sleep duration, CAD, schizophrenia, elevated LDL-C and CD33 protein levels, short telomeres, and high expression of CR1), which are crucial for setting inclusion and exclusion criteria in future population studies." (PMID 40082927, 2025).
atherosclerosis (4 papers, 2019 to 2023). A disease characterized by the build-up of fatty material and calcium deposition in the arterial wall resulting in partial or complete occlusion of the arterial lumen. "Genes such as COMP (cartilage oligomeric matrix protein), CHI3L1, PLA2G2A, P2RY12, CR1, HPSE (heparanase), PTX3 and SERPINE1 were related to atherosclerosis." (PMID 34218797, 2021). "It has been found that CD16, T-CAD, CD87, CR-1 and other GPI-anchored proteins are closely related to the occurrence and development of atherosclerosis." (PMID 31077208, 2019).
Autoimmunity (4 papers, 2016 to 2025). The occurrence of an immune reaction against the organism's own cells or tissues. "CR2 and CR1 modulate B-cell activation, and the roles of CR3 and CR4 are associated with autoimmune conditions." (PMID 39273179, 2024). "This reduction in CR1 could be inherited or acquired based on studies in autoimmunity, suggesting that evaluation of genetic variations in CR1 should be investigated in preeclampsia." (PMID 40777009, 2025).
gastric cancer (4 papers, 2017 to 2024). A primary or metastatic malignant neoplasm involving the stomach. "In gastric cancers, CR-1 expression was positively associated with lymph node metastasis, liver metastasis, and TNM stage." (PMID 31455359, 2019). "Additionally, the expression of CR-1 was found to be positively correlated with p-STAT3 expression in GC, which indicated that CR-1 plays pivotal roles in the emergence and lymphatic spread of gastric cancer (r(k) = 0.189, P = 0.002)." (PMID 39309860, 2024).
leprosy (4 papers, 2018 to 2024). Leprosy is a chronic infectious disease affecting primarily the skin and peripheral nervous system. "For example, the novel variant (E1674G) in CR1, a gene recently associated with leprosy, is a possible candidate for involvement in leprosy that deserves further follow-up." (PMID 36972292, 2023). "Of the genes tagged by novel mutations only the CR1 gene had prior evidence of a common variant impacting on human infectious disease risk, including leprosy." (PMID 36972292, 2023). "The results lead us to suggest a regulatory role for CR1 polymorphisms on mRNA and sCR1 levels, with haplotype-specific effects increasing susceptibility to leprosy, probably by enhancing parasite phagocytosis and inflammation." (PMID 30092084, 2018). "We investigated CR1 polymorphisms, gene expression and soluble CR1 levels in a case-control study with Brazilian leprosy patients, aiming to understand the role of this receptor in differential susceptibility to the disease." (PMID 30092084, 2018). "In conclusion, we suggest that CR1 polymorphisms and haplotypes enhance susceptibility to leprosy by modulating gene expression and sCR1 abundance, to increase inflammation and parasite phagocytosis." (PMID 30092084, 2018). "The present study is actually the first attempt to specifically analyse the influence of CR1 haplotypes, mRNA expression and sCR1 levels in the susceptibility to leprosy." (PMID 30092084, 2018). "In order to fill in this gap, we investigated if CR1 polymorphisms are co-responsible for differential disease susceptibility in 213 leprosy patients and 297 controls, also measuring mRNA and soluble CR1 levels." (PMID 30092084, 2018). "Despite having many common structural and regulatory variants, the CR1 gene was investigated only once in a leprosy association study in Malawi." (PMID 30092084, 2018). "In this work, we aim to fill in this gap by investigating CR1 polymorphisms, mRNA expression levels and sCR1 serum levels in Brazilian leprosy patients." (PMID 30092084, 2018). "Despite this multitude of functions, genetic association studies of infectious diseases with CR1 single nucleotide polymorphisms (SNPs) are scarce, and only one investigated this gene in leprosy, reporting a protective association with the McCoyb allele (rs17047660) in a rural region of Malawi." (PMID 30092084, 2018). "Thus, this study corroborates the importance of the CR1 receptor in the susceptibility to leprosy and is the first to bring information about CR1 polymorphisms in the Brazilian population, as well as to show the relationship between genotypes and mRNA and sCR1 levels." (PMID 30092084, 2018). "Moreover, Complement Receptor 1 (CR1) can mediate the entry of M. leprae into phagocytic cells, and its association with leprosy susceptibility has been confirmed in populations from Malawi and Brazil." (PMID 38440733, 2024). "Interestingly, we recently found polymorphisms of the CR1 gene associated with leprosy, as well as a negative correlation between the anti-inflammatory soluble CR1 and pro-inflammatory MBL levels, probably preventing inflammation." (PMID 32240160, 2020). "Indeed, several polymorphisms of genes of the complement system are associated with leprosy: mannose-binding lectin (MBL2), ficolins (FCN1, FCN2 and FCN3), the serine protease associated with them (MASP2—mannose-binding lectin serine protease 2) and complement receptor 1 (CR1, also known as CD35)." (PMID 30092084, 2018).
multiple sclerosis (4 papers, 2013 to 2025). A progressive autoimmune disorder affecting the central nervous system resulting in demyelination. "Gasque and colleagues reported CR1 localization in astrocytes in human brains from normal or multiple sclerosis patients as well as in human primary astrocyte cell cultures or cell lines." (PMID 26914463, 2016).
thalassaemia (4 papers, 2013 to 2020). "Another case-control study demonstrated that complement receptor 1 (CR1) expression required for rosette formation, is reduced on α-thalassemia red cells." (PMID 23497175, 2013). "Adjustment for CR1 copy number had no impact on the non-significant relationships between cluster volume and combined Sl and McC genotype, Sl genotype alone, McC genotype alone, gender, age, α+thalassaemia genotype or sickle cell genotype." (PMID 29259218, 2017).
vivax malaria (4 papers, 2018 to 2019). "We therefore hypothesized that CR1 genotypes associated with reduced CR1 expression on the surface of reticulocytes may confer protection against P. vivax infection, possibly reflecting positive selection on L alleles in areas exposed to or with a history of exposure to vivax malaria." (PMID 31221984, 2019). "Expression of CR1, CD55, CD59, and CD47 was also assessed on reticulocytes during falciparum and vivax malaria and healthy controls." (PMID 31533836, 2019).
coronary artery disease (3 papers, 2019 to 2024). "Similarly, in a randomized, controlled trial, 12 single nucleotide polymorphisms in the CR1 gene (which encodes complement receptor 1) were associated with the risk of incident coronary artery disease." (PMID 38978073, 2024). "CR1 polymorphisms are associated with increased risk of coronary artery disease." (PMID 33362763, 2020).
cutaneous melanoma (3 papers, 2011 to 2025). A primary melanoma arising from atypical melanocytes in the skin. "In our cohort of patients, expression of CR-1 was found both in early and late-stage cutaneous melanoma." (PMID 21863025, 2011). "We assessed the expression of CR-1 by immunohistochemistry in 37 human primary cutaneous melanomas." (PMID 21863025, 2011). "In this study we addressed the expression and the functional role of CR-1 in cutaneous melanoma." (PMID 21863025, 2011). "Surprisingly, four of the genes containing RRA missense mutaions in Uveal Melanoma (DCC, CR1, GCC2 and CLCN1) were predicted as diver genes in TCGA skin cutaneous melanoma dataset." (PMID 25903059, 2015).